CYP2A6 (cytochrome P450 family 2 subfamily A member 6)
Diseases named in the same sentence as CYP2A6 in open-access papers (continued):
Sharing a sentence is not in itself a finding about the gene and the disease.
epilepsy (3 papers, 2017 to 2022). A brain disorder characterized by episodes of abnormally increased neuronal discharge resulting in transient episodes of sensory or motor neurological dysfunction, or psychic dysfunction. "For example, among patients treated with valproic acid for epilepsy, CYP2A6*1/*4 and CYP2A6*4/*4 genotypes were associated with higher plasma valproic acid concentrations compared to non-CYP2A6*4 genotypes." (PMID 29194389, 2017). "Regarding CYP2A subfamily, Chinese people with the deletion of the CYP2A6 gene are more likely to have elevated transaminase after valproate treatment, which significantly increases the susceptibility of liver injury in patients with epilepsy caused by valproic acid." (PMID 34552491, 2021). "In particular, patients with epilepsy with the mutated genotypes of the cytochrome P450 isozymes CYP2C9 and CYP2A6 are more vulnerable to VPA-induced hepatotoxicity." (PMID 35313886, 2022). "Similarly, pediatric patients with epilepsy and who harbor the mutant alleles of CYP2C9 and CYP2A6 have a higher risk of VPA-induced hyperammonemia." (PMID 35313886, 2022).
Hepatitis (3 papers, 2004 to 2021). Inflammation of the liver. "CYP2A6 expression is closely associated with pathological grading, histologic grade, hepatitis, vascular metastasis, liver inflammation, and worse prognosis." (PMID 33455085, 2021). "Furthermore, patients with hepatitis, liver inflammation, and low body mass index also exhibited lower CYP2A6 expression levels." (PMID 33455085, 2021). "For instance, CYP1A2 is the molecular target in dihydralazine-induced hepatitis and AIH as a component of APECED, CYP2D6 in AIH-2 and in some patients with HCV infection, CYP2A6 in APECED and in a proportion of patients with HCV infection and UGT1 in some cases of AIH-2 and chronic hepatitis D or C." (PMID 15679907, 2004).
lung adenocarcinoma (3 papers, 2013 to 2025). A carcinoma that arises from the lung and is characterized by the presence of malignant glandular epithelial cells. "Considering that the whole-gene deletion of CYP2A6 is found only in lung adenocarcinoma, the potential role of CYP2A6 germline variants in lung carcinogenesis is intriguing." (PMID 36289279, 2022). "The discovery of a whole-gene deletion of CYP2A6 in patients with lung adenocarcinoma may have an important role in clinical practice and advance our understanding of CYP2A6 germline variants and their association with carcinogenesis or their susceptibility to lung adenocarcinoma." (PMID 36289279, 2022). "To assess its clinical effect, we analyzed the effect of the CYP2A6 whole-gene deletion in lung adenocarcinoma on overall survival (OS) using the Kaplan–Meier method." (PMID 36289279, 2022). "Lung adenocarcinoma patients with the CYP2A6 gene retain-type had significantly (p = 0.0099) better OS compared with squamous cell carcinoma patients with the CYP2A6 gene retain-type." (PMID 36289279, 2022). "However, it remains unclear how CYP2A6 whole-gene deletions are involved in the development of lung adenocarcinoma and their interaction with xenobiotic organisms." (PMID 36289279, 2022). "The biological significance of CYP2A6 whole-gene deletions in lung adenocarcinoma may be the modulation of the cancer phenotype, which requires further investigation and may enhance our understanding of the oncogenic mechanism of lung adenocarcinoma." (PMID 36289279, 2022). "Notably, the CYP2A6 whole-gene deletion was confirmed in 22 patients with lung adenocarcinoma but in no patients having squamous cell carcinoma." (PMID 36289279, 2022). "Notably, whole-gene deletion of CYP2A6 was confirmed in 22 patients with lung adenocarcinoma but not in any patients with squamous cell carcinoma." (PMID 36289279, 2022). "Therefore, some patients may have developed lung adenocarcinomas through a pathway unrelated to the function of CYP2A6, regardless of smoking." (PMID 36289279, 2022). "In germline DNA, a comparison of genotypes between lung adenocarcinoma (LUAD) and lung squamous cell carcinoma (LUSC) using the DME panel revealed whole-gene deletion of CYP2A6 (CYP2A6*4) in LUAD but not in LUSC." (PMID 41272073, 2025).
oral cancer (3 papers, 2013 to 2021). "People with the CYP2A6*4C/*4C genetic variant may be at lower risk of oral cancer because their genotype suppresses the activation of AN-related procarcinogens." (PMID 23983642, 2013). "A deficient in CYP2A6 may decrease the risk of oral cancer in BQ chewers in Sri Lanka." (PMID 25051199, 2014). "In terms of the cytochrome p450 (CYP) metabolism pathway, the polymorphisms of CYP-involved genes (e.g., CYP26B1, CYP1A1, CYP2A6, and CYP2E1) have been found to activate areca nut (AN)-derived nitrosamines, thereby significantly increasing the susceptibility to tobacco-induced oral cancer." (PMID 34422810, 2021).
pancreatic cancer (3 papers, 2012 to 2023). "CYP2A6, a metabolic enzyme that activates several procarcinogens, which include dietary and tobacco-specific nitrosamines, has been linked to pancreatic cancer." (PMID 37298790, 2023). "We report an association of pancreatic cancer with DNA damage and associations with specific polymorphisms in genes involved in metabolism (CYP2A6), inflammation (TNFA), and DNA damage and repair (ERCC4)." (PMID 24651674, 2014). "In our study, we found that the majority (97%) of pancreatic cancer cases possess the enzymatically active homozygous AA CYP2A6 allele compared to 75% and 89% of the healthy unrelated and related controls, respectively." (PMID 24651674, 2014). "Analysis of 22 selected SNPs in oxidative stress and DNA damage genes revealed that CYP2A6 L160H was associated with pancreatic cancer." (PMID 24651674, 2014). "The CYP2A6 L160H major allele was associated with pancreatic cancer overall (p = 0.03), as well as exhibiting significance for dominance, recessive and gene dose effects." (PMID 24651674, 2014). "Consistent with this, high levels of CYP2A6 activity were detected in patients suffering from pancreatic cancer." (PMID 37298790, 2023). "In addition, mechanistic studies of individual SNPs in CYP2A6, TNFA and ERCC4 genes would be useful to assess their contribution to the development of pancreatic cancer." (PMID 24651674, 2014).
AIDS (2 papers, 2015 to 2019). A syndrome resulting from the acquired deficiency of cellular immunity caused by the human immunodeficiency virus (HIV). "Interestingly, since CYP2A6 variants have been related to antiretroviral therapy our results might be useful for delineate therapeutic strategy accurately in Colombian HIV/AIDS patients." (PMID 31324178, 2019). "Genetic variation in CYP2A6, NR1I3 (coding for constitutive androstane receptor-CAR), and UGT2B7 has also been shown to be associated with significantly elevated efavirenz concentrations among HIV/AIDS patients." (PMID 26402689, 2015).
alcohol use disorder (2 papers, 2022 to 2023). "Indeed, individuals with alcohol use disorders have a much higher rate of nicotine metabolism and greater CYP2A6 enzyme activity than non-alcoholic smokers." (PMID 36860550, 2022).
alcoholic liver diseases (2 papers, 2016). A disorder caused by damage to the liver parenchyma due to alcohol consumption. "Meanwhile, another study found that CYP2A6 activity decreased in patients with either moderate or severe alcoholic liver disease, but not in those with only mild forms of the disease." (PMID 27203676, 2016). "Additionally, another study found that CYP2A6 clearance was reduced in patients with either moderate or severe alcoholic liver disease, but not in those with only mild disease." (PMID 27086920, 2016).
bladder cancer (2 papers, 2016 to 2025). "Together, these data suggest that CYP2A6 gene amplification and overexpression are associated with malignancy in human bladder cancer." (PMID 27902773, 2016). "To explore the correlation between CYP2A6 amplification and overexpression in human bladder cancer, we searched the Catalogue of Somatic Mutations in Cancer (COSMIC)." (PMID 27902773, 2016). "In bladder cancer, the amplification and overexpression of the CYP2A6 gene was associated with increased malignancy, namely invasiveness, both in rodents and in humans." (PMID 27902773, 2016). "A small-scale case-control study has revealed the association of CYP2A6*1/*4 or *4/ *4 genotypes with decreased susceptibility to bladder cancer; however, the relationship between CYP2A6 SNPs and bladder cancer risk has not been demonstrated by GWASs." (PMID 27902773, 2016). "Given that cigarette smoking is an environmental risk factor for bladder cancer, germ-line polymorphism of the CYP2A6 gene might be associated with an increased risk of this type of malignancy related with cigarette smoke." (PMID 27902773, 2016). "Therefore, we consider that the association of invasive bladder cancer phenotype with the amplification and potential overexpression of Cyp2a5/CYP2A6 could be highly plausible." (PMID 27902773, 2016). "Because the mouse Cyp2a5 gene is the ortholog of the human CYP2A6 gene, we also evaluated CYP2A6 copy number and protein expression in resected human bladder cancer specimens." (PMID 27902773, 2016). "Together, these findings indicate that the amplification and overexpression of the CYP2A6 gene are characteristic of human bladder cancers with increased malignancy and that CYP2A6 can be a candidate prognostic biomarker in this type of cancer." (PMID 27902773, 2016). "We analyzed copy number aberrations of the CYP2A6 and neighboring genes in human bladder cancer cell lines RT4, RT112, 5637, T24, J82, HT1197, 253J, and TCCSUP." (PMID 27902773, 2016). "Large-scale clinical trials are necessary to validate CYP2A6 potential as a useful biomarker for early detection of invasive phenotype of bladder cancer." (PMID 27902773, 2016). "Although the analyzed number of tumors was limited, our results suggest that CYP2A6 is a candidate prognostic biomarker that can be utilized for therapeutic stratification of patients with bladder cancers." (PMID 27902773, 2016). "Although our data indicate possible involvement of CYP2A6 in bladder cancer progression with invasive phenotype, it should be validated in future experimental and clinical studies." (PMID 27902773, 2016). "Therefore, our results on CYP2A6 protein expression in bladder cancer should be further validated using an antibody recognizing CYP2A6 with high specificity and sensitivity." (PMID 27902773, 2016). "The amplification of the CYP2A6 gene in primary bladder cancers was also tested by qPCR which confirmed that CYP2A6 was amplified in one papillary tumor and five invasive tumors (copy number gain > +1), and the difference was statistically significant (p = 0.0085)." (PMID 27902773, 2016). "Therefore, we investigated CYP2A6 gene amplification and protein expression in human bladder cancer." (PMID 27902773, 2016). "Therefore, we next examined CYP2A6 copy number and protein expression in human bladder cancer." (PMID 27902773, 2016). "The results indicate that 4 out of 113 of bladder cancer samples (3.54%) had copy number gain, and 2 of them (50%) demonstrated CYP2A6 overexpression, suggesting that CYP2A6 protein levels may be regulated by other mechanisms at the transcriptional, translational, or epigenetic levels." (PMID 27902773, 2016). "However, that study did not discriminate between non-invasive and invasive bladder cancers; therefore, CYP2A6 contribution to the risk of developing invasive bladder cancer phenotype could not be clearly determined." (PMID 27902773, 2016).
bladder cancer (continued). "A search of available public databases, such as GEO and Oncomine, did not produce any results on the correlation of CYP2A6 expression levels with bladder cancer disease stage." (PMID 27902773, 2016). "The amplification of CYP2A6 and CYP2A7 (copy number 3 or more) could be merely detected in one bladder cancer cell line." (PMID 27902773, 2016). "The amplification of the CYP2A6 locus was not clearly detected in human bladder cancer cell lines, which might be due to cell line origin from fully metastasized cancer." (PMID 27902773, 2016).
chronic obstructive pulmonary disease (2 papers, 2012 to 2023). A chronic and progressive lung disorder characterized by the loss of elasticity of the bronchial tree and the air sacs, destruction of the air sacs wall, thickening of the bronchial wall, and mucous accumulation in the bronchial tree. "Highly significant DEGs including CYP1A1, HHIP (hedgehog interacting protein), MUC5AC, and CYP2A6 might be related to the pathophysiology of chronic obstructive pulmonary disease." (PMID 38137330, 2023).
Cirrhosis (2 papers, 2016). A chronic disorder of the liver in which liver tissue becomes scarred and is partially replaced by regenerative nodules and fibrotic tissue resulting in loss of liver function. "Several previous studies reported that the activities of several CYPs, including CYP1A2, CYP2A6, CYP2D6, CYP2C19, CYP2E1, and CYP3A were decreased in cirrhosis patients relative to healthy subjects." (PMID 27203676, 2016). "In terms of Vmax, CYP2A6, CYP2B6, CYP2C9, CYP2D6, CYP2E1, and CYP3A4/5 were increased, while the Vmax values of CYP1A2 and CYP2C8 were decreased in both the cirrhosis and fibrosis groups compared to control subjects." (PMID 27203676, 2016). "Compared with controls, the Km values of CYP1A2, CYP2A6, CYP2B6, CYP2C8, CYP2C19, CYP2E1, and CYP3A4/5 were higher in both in fibrosis and cirrhosis groups." (PMID 27203676, 2016). "By contrast, our present study showed that CYP2A6 clearances were not altered in the fibrosis or cirrhosis subgroups of HCC patients." (PMID 27086920, 2016). "In contrast, our study showed that CYP2A6 activity was not changed in the fibrosis or cirrhosis subgroups of HCC patients, which again demonstrates the differences that may exist between simple cirrhosis and cirrhosis that accompanies HCC." (PMID 27203676, 2016).
colorectal tumor (2 papers, 2021). "The CYP2A6 genotypes could be applicable to future personalized treatments for colorectal tumor chemoprevention with daily aspirin." (PMID 34193316, 2021). "The effectiveness of chemoprevention using daily aspirin to reduce the risk the colorectal tumors was found to be inversely related to the estimated activities of CYP2A6 phenotypes (based on the presence/absence of CYP2A6*1 alleles) among a Japanese cohort without familial adenomatous polyposis." (PMID 34193316, 2021). "Collectively, when subjects with familial adenomatous polyposis were excluded, the presence of the wild-type allele of polymorphic CYP2A6 apparently led to a reduction in the chemopreventive effects of daily aspirin on the sporadic development of colorectal tumors in nonsmokers." (PMID 34193316, 2021). "However, the chemopreventive effects of aspirin against colorectal tumor recurrence was suggested to be associated with those who did not carry a wild-type CYP2A6*1 allele." (PMID 34193316, 2021). "Aspirin chemoprevention for colorectal tumor recurrence was significantly observed (P < 0.05) in the male nonsmoker subset of the J-CAPP cohort genotyped for CYP2A6*1/*4 and *4,*7,*9/*4,*7,*9, i.e., the putative impaired phenotype." (PMID 34193316, 2021).
cutis laxa (2 papers, 2025 to 2026). Cutis laxa (CL) is an inherited or acquired connective tissue disorder characterized by wrinkled, redundant and sagging inelastic skin associated with skeletal and developmental anomalies and, in some cases, with severe systemic involvement. "This marker is located in CYP2A6 as well as in an enhancer region of LTBP4, which is associated with cutis laxa." (PMID 40831500, 2025). "However, the pleiotropy of CYP2A6 and LTBP4 may be the molecular reason why tobacco smoking can lead to a rapid, severe loss of lung function in individuals with LTBP4-related cutis laxa." (PMID 40831500, 2025).
dyslipidemia (2 papers, 2022 to 2024). "It is found that the genotype polymorphisms of patients, such as CYP2C9 and CYP2A6, were important factors for dyslipidemia." (PMID 38628642, 2024).
emphysema (2 papers, 2019 to 2021). "The second gene in this emphysema analysis was CYP2A6 (cytochrome P450 family 2 subfamily A member 6) from a locus previously identified in GWAS of smoking behavior and COPD." (PMID 30940135, 2019).
Hypertension (2 papers, 2021 to 2022). The presence of chronic increased pressure in the systemic arterial system. "Nifedipine is a dihydropyridine L-type calcium channel blocker used to treat hypertension; its target gene (CACNA1S) and primary enzyme genes (CYP1A1 and CYP2A6) all had deleterious variants in our population." (PMID 35280256, 2021).
Insulin resistance (2 papers, 2022 to 2026). Increased resistance towards insulin, that is, diminished effectiveness of insulin in reducing blood glucose levels. "Additionally, insulin resistance is more likely to occur in men, while estrogen can affect enzyme (CYP2A6) activity and promote nicotine metabolism for women." (PMID 35937829, 2022).
non-small cell lung carcinoma (2 papers, 2011). A group of at least three distinct histological types of lung cancer, including non-small cell squamous cell carcinoma, adenocarcinoma, and large cell carcinoma. "A previous study reported that non-small cell lung cancer patients with CYP2A6*4 alleles, which complete lack relevant enzymatic activity, show significantly lower plasma concentrations of 5-FU." (PMID 21326246, 2011). "In addition, our present results are supported by the findings that CYP2A6*4 reduces plasma 5-FU concentration and increases the area of under the concentration-time curve (AUC) and Cmax for tegafur in non-small cell lung cancer patients treated with S-1 alone or in combination with cisplatin." (PMID 21364592, 2011).
ovarian carcinoma (2 papers, 2017 to 2023). A malignant neoplasm originating from the surface ovarian epithelium. "In contrast, high mRNA expression of CYP2A6, CYP2C9, CYP2J2, CYP3A4, CYP3A5, CYP3A7, and CYP3A43 connoted a good prognosis for ovarian cancer patients." (PMID 38001897, 2023).
rheumatoid arthritis (2 papers, 2017 to 2023). A chronic, systemic autoimmune disorder characterized by inflammation in the synovial membranes and articular surfaces. "Novel gene-longevity associations included genes MICA/B (a locus previously linked to autoimmune conditions rheumatoid arthritis and multiple sclerosis), TOX, ZW10, SEMA6D, EGLN2/CYP2A6, EXOC3L2/MARK4 and C20orf187." (PMID 29227965, 2017).
squamous cell carcinoma (2 papers, 2009 to 2022). A carcinoma arising from squamous epithelial cells. "The CYP2A6 rs1801272 polymorphism, which results in an amino acid change from Leu to His, was significantly associated with a decreased risk for squamous cell carcinoma, a strictly smoking-related malignancy." (PMID 19479063, 2009). "Conversely, squamous cell carcinoma that develops in squamous epithelial cells may be directly affected by smoking in a dose-dependent manner while maintaining the function of the CYP2A6 variants." (PMID 36289279, 2022). "In addition, CYP1B1 and CYP2A6 polymorphisms were inversely associated with adenocarcinoma and squamous cell carcinoma risk, respectively." (PMID 19479063, 2009). "Conversely, whole-gene deletion of CYP2A6 was associated with adenocarcinoma but not squamous cell carcinoma." (PMID 36289279, 2022). "A limitation of the present study is that the absence of the CYP2A6 whole-gene deletion in patients with squamous cell carcinoma is debatable because our results were derived from a small hospital-based sample." (PMID 36289279, 2022). "Notably, a whole-gene deletion of CYP2A6 was detected in 22 patients with adenocarcinoma but in no patient with squamous cell carcinoma." (PMID 36289279, 2022).